ENSG00000212461
Synonyms: LOC124900332
Gene: Small nucleolar RNA gene on chromosome 12 (71,639,355 to 71,639,483, forward strand). Ensembl gene ENSG00000212461.
Gene Ontology:
Biological process: RNA processing
Cellular component: nucleolus
Homologues: Orthologues: rat LOC120102662 (74% identical), rat LOC120099020 (73% identical), rat LOC120100413 (71% identical), rat LOC120101319 (70% identical), rat LOC120094514 (69% identical), rat LOC120100438 (68% identical), rat LOC120101330 (68% identical), rat LOC120103336 (67% identical), mouse Gm26184 (65% identical), rat LOC120103343 (64% identical), rat LOC120096406 (63% identical), rat LOC120097624 (62% identical), and 7 more. Paralogues in human: SNORA17B (57% identical).